S100A7A (S100 calcium binding protein A7A)
Description:
May be involved in epidermal differentiation and inflammation and might therefore be important for the pathogenesis of psoriasis and other diseases.
Synonyms: S100A15; S100A7L1; S100A7f; NICE-2; NICE2
Tractability: No criterion of Open Targets' tractability assessment is met for any kind of drug.
Gene: Protein-coding gene on chromosome 1 (153,416,520 to 153,423,222, forward strand). Ensembl gene ENSG00000184330.
Subcellular location: Cytoplasm
Subcellular location (Human Protein Atlas): Cytosol
Pathways (Reactome):
Immune System: Metal sequestration by antimicrobial proteins
Gene Ontology:
Molecular function: identical protein binding; protein binding; calcium ion binding; calcium-dependent protein binding; transition metal ion binding
Biological process: endothelial cell migration
Cellular component: cytoplasm
Genetic constraint (gnomAD): Loss-of-function variants: 5 observed, 5.19 expected, observed/expected ratio (o/e) 0.96, 90% interval 0.5 to 1.78. That is too few expected variants to judge how well the gene tolerates losing a copy. Missense variants: 159 observed, 129.31 expected, observed/expected ratio (o/e) 1.23, 90% interval 1.08 to 1.4. Synonymous variants: 52 observed, 48.78 expected, observed/expected ratio (o/e) 1.07, 90% interval 0.85 to 1.34.
Homologues: Orthologues: chimpanzee S100A7A (95% identical), tropical clawed frog s100a11 (25% identical), zebrafish s100t (25% identical), zebrafish s100a10a (24% identical), zebrafish s100s (23% identical). Paralogues in human: S100A7 (94% identical), S100A11 (31% identical), S100A10 (26% identical), S100A9 (25% identical), S100Z (25% identical), S100A16 (24% identical), S100A4 (24% identical), S100B (24% identical), S100G (24% identical), S100A1 (23% identical), S100A2 (23% identical), S100A5 (23% identical), and 9 more.
Diseases named in the same sentence as S100A7A in open-access papers:
S100A7A is named in the same sentence as 21 diseases in open-access papers, as found by Europe PMC text mining. Sharing a sentence is not in itself a finding about the gene and the disease. The quoted sentences say what the papers report.
psoriasis (22 papers, 2014 to 2025). An autoimmune condition characterized by red, well-delineated plaques with silvery scales that are usually on the extensor surfaces and scalp. "S100a7a and S100a14, two genes associated with the severity psoriasis, showed decreased expression levels in the SS/PVA-treated group, which led to an improvement in the psoriatic condition." (PMID 36613589, 2022). "These include S100a7a (psoriasin) and S100a9, both encoding antimicrobial and/or chemotactic proteins which are expressed under a variety of epidermal insults including psoriasis and wound healing." (PMID 29378633, 2018). "Interestingly, among the psoriasis-associated S100 protein-coding genes, S100A7A (also known as S100A15) was the most upregulated gene in the PE skin." (PMID 35563374, 2022). "However, it is interesting to note that altered expression of genes including Tpsab1, Shh, S100a7a and Il20, which are associated with tumorigenesis or psoriasis, was observed in the microarray analysis." (PMID 27756876, 2016). "The upregulation of S100A7A may enhance its immunoregulatory function and be associated with inflammatory responses and keratinocyte differentiation, a phenomenon particularly pronounced in proliferative skin disorders such as psoriasis." (PMID 40141352, 2025). "The co-expression shifts of HKGs with psoriasis-associated genes (e.g., DEFB103A/B, S100A7A, IL36RN) further demonstrate their regulatory influence." (PMID 40959079, 2025). "Sericin decreased the expression of the S100a7a and S100a14 genes, which are involved in the severity of psoriasis." (PMID 36613589, 2022). "Top up-regulated DEGs in CP vs C include previously identified psoriasis-associated genes such as IL36A/G, SPRR2A/B/F, SERPINB4, S100A7A, S100A9, and IL17F while top down-regulated DEGs include SERTM1, IL6, and ADAMTS16." (PMID 30054515, 2018). "S100A7 and S100A7A are constitutively expressed in the skin and can be present at high levels during disease or inflammation, such as, for example, psoriasis." (PMID 27355424, 2016). "The strong upregulation of S100A7A could be characterized by increased immune regulatory functions as a result of psoriasis and other hyperproliferative skin conditions, featuring impaired epidermal differentiation." (PMID 35524260, 2022). "For example, S100A4 is involved in autoimmune pancreatitis, S100A11, S100A8 and S100A9 in rheumatoid arthritis, S100A1 in hypoxia-induced inflammatory response in cardiomyocytes, S100A12 in Crohn’s disease, S100A7 and S100A7A in psoriasis, S100A8, S100A9 and S100A12 in systemic lupus erythematosus." (PMID 30018736, 2018). "Comparing gene expression in obese versus non-obese skin showed greater gene expression of S100A7A, encoding a calcium binding protein involved in psoriasis, and CORIN encoding a natriuretic peptide converting enzyme, which is expressed in the dermis and is involved in specifying skin colour." (PMID 32826922, 2020). "S100A7A and S100A12, part of the S100 protein family, are primarily involved in inflammatory processes and are upregulated in psoriasis, thereby exacerbating inflammation." (PMID 40959079, 2025). "These genes include genes that are well known to be involved in psoriasis, including LCE3D, LCE3E, SERPINB4, and S100A7A, genes involved in activation and proliferation of keratinocytes, modulation of host immune response, and antimicrobial defense." (PMID 30054515, 2018). "IL-17 also induced a number of anti-microbial peptides, including S100A12, S100A7A, SERPINB4, SERBINB3, which are highly expressed in psoriasis, as has been described previously." (PMID 24587313, 2014). "In addition, IL-36G upregulates the expression of CCN1 and S100A7A, leading to the production of excessive pro-inflammatory factors by the cells, including IL-1, IL-6, IL-8, IL-36, and TNF, which promotes psoriasis." (PMID 40735322, 2025).
psoriasis (continued). "Interestingly, S100A7A is highly increased in psoriatic skin and shares near-complete homology with S100A7 (Psoriasin), which has a well-established role in the pathogenesis of psoriasis and is also increased in atopic dermatitis." (PMID 31059533, 2019).
asthma (2 papers, 2014 to 2021). "Furthermore, several genes (SH3KBP1, CRNN, FLG, S100A7A) related to allergic inflammation were either induced in allergic rhinitis patients with or without asthma (SH3KB1) or in allergic rhinitis patients only (CRNN, FLG, S100A7A)." (PMID 24475887, 2014).
cholesteatoma (2 papers, 2012 to 2014). A pathologic process characterized by the proliferation of keratinizing squamous epithelium resulting in the accumulation of keratin and cells in the middle ear and/or mastoid. "Genes which were important for inflammation are for example KRT 6 B, SPP1, and S100A7A are highly up-regulated in cholesteatoma compared to external auditory skin." (PMID 23285167, 2012). "Cholesteatoma contained high levels of pro-inflammatory S100 proteins, such as S100A7A and S100A7." (PMID 25093596, 2014).
lung carcinoma (2 papers, 2018 to 2021). "However, the roles of S100A1, S100A3, S100A7A, S100A12, S10016, and S100G proteins in lung cancer are rarely reported." (PMID 29607329, 2018).
ovarian carcinoma (2 papers, 2018 to 2021). A malignant neoplasm originating from the surface ovarian epithelium. "Whereas, some other S100 family members, including S100A3, S100A5, S100A7, S100A7A, S100A8, S100A16 and S100G are less reported in ovarian carcinoma." (PMID 30558666, 2018).
bladder cancer (1 paper, 2021). "Previously, a correlation of S100A7A (also known as psoriasin) expression with poor bladder cancer survival was seen." (PMID 34359804, 2021).
breast carcinoma (1 paper, 2015). "ERBB2 is a major gene that determine the molecular subtype of breast cancer and S100A7A has been shown to be down-regulated in estrogen receptor negative tumors." (PMID 26669540, 2015). "Our observation can generate a hypothesis that ERBB2 and S100A7A-mediated MMP13 expression can contribute to the subtype-specific spatial growth patterns in breast cancer." (PMID 26669540, 2015).
infection (2 papers, 2017 to 2022). The state of being infected such as from the introduction of a foreign agent such as serum, vaccine, antigenic substance or organism. "We observed lower expression of S100a7a at the mRNA, and protein levels at 24 h and 7 days post infection in urinary bladders of diabetic compared to control mice." (PMID 36127330, 2022). "Mtb-infection also failed to induce S100A7A expression in AMΦs, while DEFB4 induction ranged from 0.84–14.08 fold in three healthy donors." (PMID 28863187, 2017).
tumor (2 papers, 2013 to 2023). "Notably, S100A15 (also called S100A7A; epidermal maturation and antimicrobial defense) was up-regulated with tumor progression and reversed to normal after chemotherapy." (PMID 23451142, 2013). "As S100A5, S100A7, S100A7A, S100Z, TCHHL1, and S100G are ubiquitously expressed at low levels in both tumor and paratumor samples, they were not included in the following analyses." (PMID 37133437, 2023).
S100A7A also shares sentences with these, for which no sentence is quoted: melanoma (3 papers); cancer (2); acne (1); allergic rhinitis (1); atopic dermatitis (1); autoimmune pancreatitis (1); Crohn disease (1); endometrial carcinoma (1); inflammatory skin disease (1); papilloma (1); rheumatoid arthritis (1); systemic lupus erythematosus (1).